IDH1 (isocitrate dehydrogenase (NADP(+)) 1)
Diseases named in the same sentence as IDH1 in open-access papers (continued):
Sharing a sentence is not in itself a finding about the gene and the disease.
glioma (continued). "Comparing IDH1-mutated with IDH1-wildtype gliomas, the following features of the ADC histogram achieved statistical significance: lower percentiles (p10 and p25), modus, standard deviation, maximum, skewness and entropy." (PMID 35884457, 2022). "Isocitrate dehydrogenase 1 and 2 (IDH1/2) are enzymes recurrently mutated in various types of cancer, including glioma, cholangiocarcinoma, chondrosarcoma, and acute myeloid leukemia." (PMID 34967233, 2022). "We also detected DNA 5mC in glioma from the same set of patients; and by excluding IDH1 mutation, we observed a significant reduction in human Anaplastic Astrocytomas and glioblastomas, but not in Astrocytoma tissues." (PMID 35501312, 2022). "IDH1/2 mutation and chromosome 1p/19q codel represent driver events during glioma tumorigenesis and are associated with better survival rates in glioma." (PMID 35734424, 2022). "Currently, analysis of the expression of isocitrate dehydrogenase [NADP(+)] 1 (IDH1) and the identification of its main mutations (e.g., R132H) were used for glioma diagnosis and prognosis." (PMID 35574309, 2022). "The discovery of a disease-defining and prognostically favourable point mutation in IDH1 codon 132 has considerably altered our understanding of glioma biology." (PMID 35692047, 2022). "Recent research has uncovered a unique metabolic vulnerability in the sphingolipid pathways of gliomas that possess the IDH1 mutation." (PMID 36012521, 2022). "In this regard, IDH305 (Novartis) targets IDH1 mutations, and ongoing trials are presently being conducted in gliomas and other malignancies with IDH1 R132 mutations (NCT02381886)." (PMID 35912242, 2022). "Ivosidenib is trying to expand to solid and other hematological tumors with an IDH1 mutation, such as glioma, pancreatic adenocarcinoma, and myedysplastic syndrome (NCT02073994, NCT05209074, and NCT03839771)." (PMID 36254250, 2022). "In this study, we have explored the expression and localization of FABP7 in current separated grade of glioma with focus on IDH1 mutation and how FABP7 regulates cellular activity of GB focusing on the epigenetic regulation of caveolin‐1." (PMID 34716958, 2022). "Mounting evidence has demonstrated that the molecular characteristics of gliomas include mutated isocitrate dehydrogenase 1 and 2 genes (IDH1/2) and co-deletion of 1p/19q." (PMID 35309512, 2022). "Surprisingly, a study suggested that elevated ECM stiffness can independently contribute to the aggressiveness and recurrence of GBM and predict a worse outcome of glioma patients via bypassing the isocitrate dehydrogenase 1 (IDH1) mutational protection." (PMID 35528238, 2022). "In a study on cell cultures of gliomas with both the wild type and the IDH1 mutation, indirect evidence was found that glutathione peroxidase levels are altered in cells with the IDH1 mutation." (PMID 36289655, 2022). "A total of 70–80% of grade II and III gliomas and 80–90% of grade IV gliomas (also called glioblastomas) possess IDH1 mutations (IDH1mt)." (PMID 36159801, 2022). "Our data suggest that the cytotoxic effects of NAMPT inhibitors are, in part, independent of IDH1 status, thus possibly limiting their suitability as a selective treatment option for IDH1 mutated glioma." (PMID 35628596, 2022). "In gliomas, frequent IDH1/2 mutations are also observed but progress is even more limited, possibly owing to insufficient CNS penetration, an irreversible epigenetic landscape, or lack of tumor addiction to IDH1/2 mutations." (PMID 35426374, 2022). "In primary brain tumors, glioma CIMP (G-CIMP) is highly associated with mutations in genes encoding isocitrate dehydrogenase (IDH1/2), and the IDH mutation, when overexpressed in normal astrocytes, can recapitulate the G-CIMP hypermethylation pattern." (PMID 35392283, 2022).
glioma (continued). "IDH1/IDH2 mutation is a common feature of gliomas and is associated with a glioma-CpG island methylator phenotype (CIMP)." (PMID 36360312, 2022). "In some gliomas, point mutations in isocitrate dehydrogenase type 1 (IDH1) occur during early cancer development." (PMID 35651800, 2022). "Mutations in IDH1 characterize the majority of lower-grade gliomas in adults and define a subtype associated with a favorable prognosis." (PMID 36727078, 2022). "Harboring the IDH1 mutation is linked to improved survival, and this holds true even in the setting of high-grade gliomas." (PMID 35086512, 2022). "Although from a small sample, these data suggest that patients with Ollier disease harboring the IDH1 R132H mutation in enchondroma are at major risk of developing gliomas, compared to enchondromatosis patients with the IDH R132C mutation in enchondroma." (PMID 35884525, 2022). "On the other hand, the SET domain containing 2 (SETD2) was associated with a low risk of CAT across cancers, and isocitrate dehydrogenase (NADP(+)) 1 (IDH1) was associated with a low risk of CAT in glioma." (PMID 35565252, 2022). "Glioma classification is moving from histopathology to genomics, transcriptomics and epigenomics classifiers, with isocitrate dehydrogenase (IDH1/2) mutations and a chromosome 1p and 19q codeletion, among others, now commonly used for diagnosis and prognosis." (PMID 36050369, 2022). "In primary IDH1-R132H grade II/III gliomas, less infiltration of CD8+ T cells in the TME is associated with long-term survival." (PMID 35769466, 2022). "With the increased availability of NGS in clinical diagnostics, it is likely that there will be improved detection of the dual IDH1/2 mutations in glioma, and a greater understanding of its influence on survival." (PMID 36286062, 2022). "IDH1 mutations have recently been discovered in nearly 80% of gliomas or glioblastomas and nearly 20% of acute myeloid leukemias, eliciting new interest in defining IDH1 functions in vivo." (PMID 35132321, 2022). "Somatic IDH1/IDH2 mutations occur in approximately 80% of gliomas and secondary glioblastomas but in less than 10% of primary glioblastomas." (PMID 36360312, 2022). "The fact that wild-type IDH1 is causally related to clinical cases of low-grade gliomas lends support to our own findings of its upregulation in the Ezh2 gain-of-function ‘tumors’, presenting similar features." (PMID 35395831, 2022). "P9 shows a benign variant (c.532G>A p.Val178Ile) in exon 6 of the IDH1 gene, with a frequency of 5% and 194 homozygotes (ExAC_nontcga_NFE) described in association with hematopoietic neoplasms, gliomas, thyroid tumors, and meningioma (COSM97131)." (PMID 35456430, 2022). "Conversely, hotspot mutations in IDH1/2 are rare in older adolescent and represent the lower age spectrum of adult gliomas." (PMID 35536420, 2022). "The investigated ddPCR-based assays enable the detection of diagnostically relevant glioma-associated mutations in the IDH1, IDH2, H3-3A, BRAF, and PRKCA genes, as well as in the TERT promoter." (PMID 35361262, 2022). "IDH1 mutation was added into the 2016 WHO glioma classification, and patients with this mutation develop poor prognosis compared with the IDH wild-type patients." (PMID 36311792, 2022). "One recent phase 1 clinical trial studied the efficacy of the IDH1 R132H mutant peptide vaccine (NOA-16) in IDH1 mutated grade III–IV gliomas, which led to both mutation-specific T cell and humoral immune responses (NCT02454634)." (PMID 36011015, 2022).
glioma (continued). "Preclinical trials using vorasidenib in orthoptic mouse xenograft models of human IDH1/2 mutated glioma demonstrated improved BBB penetration, significant 2-HG suppression, and inhibition of tumor growth." (PMID 35158978, 2022). "Two mutations (IDH1/2 mutations and 1p19q co-deletion) are routinely used for the diagnosis and classification of gliomas." (PMID 35845613, 2022). "Since lower grade, 1p/19q codeletion, MGMT promoter methylation, and IDH1 mutation were the major favorable prognostic markers for glioma, a subgroup analysis based on the status of these parameters was performed in both TCGA and CGGA cohort." (PMID 35990696, 2022). "There was a significant association between glioma grading and IDH1/2 (p < 0.05), 1p/19q (p < 0.05), MGMT (p < 0.05), Ki67 (p < 0.01), and MAGED2 (p < 0.01)." (PMID 35892426, 2022). "Increasing evidence has demonstrated that the molecular characteristics of gliomas include mutated isocitrate dehydrogenase 1 and 2 genes (IDH1/2) and co-deletion of 1p/19q." (PMID 36465369, 2022). "The NOA16 trial was a phase I study testing an IDH1-specific peptide vaccine among patients with IDH1-mutated gliomas." (PMID 35875065, 2022). "Of note, in contrast to WHO II and III supratentorial glial tumours, IDH-1 mutations are suggested to be less common in infratentorial gliomas, even in lower grades (WHO II and III 8%) and LOH 1p19q is almost absent." (PMID 34342680, 2022). "Analysis of All glioma tumors highlighted two genes involved in pyruvate metabolism that were associated with IDH1; these were glyoxalase I (GLO1) and pyruvate carboxylase (PC)." (PMID 35877430, 2022). "This translational study explores multi-tracer PET imaging for the non-invasive detection of the IDH1 mutation which is a positive prognostic factor in glioma." (PMID 35303961, 2022). "in a heterogeneous cohort of gliomas [n = 100 (grade-I I = 11; grade-3 = 8 and grade IV: 81)] used MRI-based radiomic features to predict IDH1 Mutation Status in Gliomas using a gradient tree boost machine learning classifier." (PMID 36276136, 2022). "As a prognostic marker, several studies have found that IDH1/2 mutations are linked to prolonged patient survival and therapeutic response amongst patients with gliomas and GBM." (PMID 36643416, 2022). "The decrease in the activity of lactate dehydrogenase 4.5 in the tissues of gliomas with an IDH1 mutation leads to the decrease in anaerobic glycolysis indirectly activating the pentose phosphate pathway." (PMID 35625744, 2022). "High GMFG expression significantly correlated with the malignancy of gliomas and was strongly associated with IDH1/2 wild-type, 1p19q codeletion, and ME subtypes." (PMID 35845613, 2022). "We postulate that the rate of dual IDH1/2 mutations in gliomas is underestimated, due to the use of IDH1 R132H immunohistochemistry, and anticipate that its detection will increase with the more widespread use of NGS technologies in cancer diagnosis." (PMID 36286062, 2022). "Considering the effects of methylation associated with gene expressions in glioma, especially the IDH1 status, we evaluated the methylation levels of these signature-related genes using the DiseaseMeth2.0 database." (PMID 35647198, 2022). "In the present review, we examine the “truncal” role of IDH mutations in gliomagenesis, giving hints on the different therapeutic strategies targeting IDH1/2-mutated gliomas." (PMID 35267433, 2022). "recently conducted a multiplexed sequencing on 242 glioma tumors for mutations of IDH1/2, H3F3A, HIST1H3B, and TERT genes concomitantly to RAS isotypes." (PMID 36358803, 2022).
glioma (continued). "It had been proved that gliomas with the IDH1 mutation were more sensitive to chemotherapy and radiotherapy, resulting in a better prognosis." (PMID 36778912, 2022). "IDH1 mutation is intrinsically linked to glioma subtype as oligodendroglioma is diagnosed based on the presence of both the 1p/19q co-deletion and mutation of either IDH1 or IDH272." (PMID 35017538, 2022). "This study demonstrates the feasibility of BEAMing technology to detect plasma IDH1 mutations in patients with IDH1-mutant gliomas for the first time." (PMID 35740557, 2022). "PD-L1 expression, which is perhaps the most researched immune checkpoint receptor ligand, is reduced on glioma cells harboring a mutation of isocitrate dehydrogenase gene 1 (IDH1) and is increased after loss of phosphatase and tensin homolog (PTEN)." (PMID 36186781, 2022). "Janus kinase and microtubule-interacting protein 1; marlin-1 (JAKMIP1) was identified as being associated with IDH1 expression in the All gliomas analysis." (PMID 35877430, 2022). "Compared to the wild-type IDH1, its mutant counterpart caused decreased plasma glutamate in glioma patients." (PMID 36295820, 2022). "IDH1/2 mutational status is therefore an important molecular distinction in adult gliomas due to its prognostic value and potential as a drug target." (PMID 36286062, 2022). "According to previous reports, IDH1 mutation is common in many malignant tumors, such as glioma, acute myeloid leukemia, thyroid cancer and chondroma." (PMID 35601497, 2022). "Two hotspots for IDH1/IDH2 mutation have been described in gliomas: IDH1 codon 132 (p.R132) and IDH2 codon 172 (p.R172)." (PMID 36360312, 2022). "The most studied example linking genetic alterations to gliomas metabolic changes is the acquired mutation in IDH1 and/or IDH2 genes." (PMID 35912242, 2022). "BEAMing detected IDH1 mutations in the plasma of patients with gliomas, with a modest clinical sensitivity (true positivity rate) but with 100% clinical specificity, with complete agreement between the mutant loci detected in tumor and plasma." (PMID 35740557, 2022). "Isocitrate dehydrogenase 1(IDH1) mutation in glioma cells leads to an increased level of 24(S)-hydroxycholesterol (24-OHC), which activates liver X receptors (LXRs)." (PMID 36506554, 2022). "A subset of gliomas, those showing IDH1 mutations, are characterized by extensive DNA hypermethylation of CpG islands, a phenomenon referred to as glioma CpG island methylator phenotype (glioma CIMP)." (PMID 35628470, 2022). "miR-215 overexpression, miR-637 suppression, and IDH1 wildtype were associated with the poor prognosis of patients with glioma." (PMID 36221066, 2022). "Mutations in the isocitrate dehydrogenase (IDH) 1 gene are commonly found in human glioma, with most lower-grade gliomas harboring a recurrent point mutation (IDH1 R132H)." (PMID 35086512, 2022). "Certain glioma-associated biomarkers can be assessed by immunohistochemistry, including IDH1 R132H, H3 K27M and H3 G34R/V, loss of nuclear ATRX expression, and BRAF V600E mutation." (PMID 35361262, 2022). "Specifically, IDH1 or IDH2 are usually mutated in WHO grade II/III glioma or secondary GBM patients, mainly in the frontal lobe (75%) and temporal lobe (40%)." (PMID 36556190, 2022). "Gliomas harboring isocitrate dehydrogenase 1 (IDH1) mutations have been reported to have a decreased ability to compensate for reactive oxygen species (ROS), due to reduced IDH1‐wild‐type activity and concomitant low NADPH." (PMID 34856072, 2022). "Established molecular biomarkers in supratentorial glioma, such as IDH-1 mutation and the loss of heterozygosity of 1p19q (LOH 1p19q) are of high importance in the diagnostic and prognostic assessment." (PMID 34342680, 2022).
glioma (continued). "This represents an important finding that has the potential to refine the utility of WGMA to predict the IDH1/IDH2 mutation status of gliomas, thus improving diagnostic yield and efficiency of laboratory testing compared to single analyte IDH1/IDH2 tests." (PMID 36360312, 2022). "Determining the IDH1/2 mutational status is useful to establish RIG diagnosis when the primary tumor is glioma." (PMID 35505351, 2022). "Glioma biomarkers of predictive value for PARPi therapeutic efficacy include IDH1/2 mutations, a low BRCA1 expression, aberrant ATM or ATR signaling, MYC overexpression, and inactivation of mismatch repair genes, especially MSH6." (PMID 35406593, 2022). "Our results showed that CIMP was more frequent in isocitrate dehydrogenase 1 (IDH1)-mutated gliomas (OR 229.07; 95% CI 138.72–378.26) and 1p19q loss of heterozygosis (LOH) gliomas (OR 5.65; 95% CI 2.66–12.01)." (PMID 36181110, 2022). "The practicability and specificity of the risk model in both IDH1mt and IDH1-wildtype (wtIDH1) gliomas in TCGA and CGGA were evaluated." (PMID 36159801, 2022). "This is a new finding, shedding light on the relationship between IDH1 mutation and methylation alterations in gliomas." (PMID 36233525, 2022). "While our multivariable models adjust for tumour subtype, we investigated age-associations of ATRX and IDH1 SNV mutation frequency in lower grade gliomas in greater detail." (PMID 35017538, 2022). "Next, we performed an integrated analysis of EGFR amplification and molecular glioma hallmarks: IDH1/2 mutations, TERT promoter mutations, MGMT promoter methylation, and LOH 1p/19q." (PMID 35453544, 2022). "A recent study found that the survival of IDH1 mutated glioma cells was dependent on the de novo synthesis of pyrimidine." (PMID 36568190, 2022). "Clinical applications of 2HG MRS have shown diagnostic utility in identifying gliomas that express a range of IDH1/2 mutations and reliably quantifying concentrations in excess of 1 mM." (PMID 35672531, 2022). "A mutant IDH2 gene (IDH2 R172K or R172M) has additionally been identified in glioma subsets, although less frequently than IDH1 mutations." (PMID 35804976, 2022). "These patterns partially resemble methylation patterns found in IDH1-mutated gliomas, although only 17 genes were concordantly hypermethylated and downregulated in both tumor types." (PMID 35628470, 2022). "According to the WHO classification of glioma (as of 2016), C11orf95–RELA fusion, IDH1/2 mutation, H3-K27M mutation, and 1p/19q deletion are categorized as diagnostic biomarkers defining distinct glioma entities." (PMID 35989351, 2022). "Phase I clinical trials of BAY1436032 are ongoing in patients with advanced solid tumors, including glioma with the IDH1 mutation (NCT02746081)." (PMID 35628385, 2022). "This study examines the effectiveness of olaparib in treating cholangiocarcinoma, glioma, and solid tumors which have mutations in the IDH1 or IDH2 gene; unable to treat or control with current treatments; have migrated to other parts of the body." (PMID 35873570, 2022). "As a result, the pH of the tissue is normalized which explains the less aggressive biological behavior of gliomas with an IDH1 mutation." (PMID 35625744, 2022). "Since its initial discovery in gliomas, IDH1 and IDH2 mutations have been described in a variety of other cancers including acute myeloid leukaemia, thyroid carcinomas, cartilaginous tumours such as enchondroma and chondrosarcoma, and cholangiocarcinomas." (PMID 36286062, 2022). "Analysis of the collected data showed that among glial tumors, cells with the IDH1/2 mutation showed less fluorescence compared with cells without this mutation." (PMID 35055109, 2022). "Glioma is a highly heterogeneous tumor with multiple genetic characteristics, including isocitrate dehydrogenase (IDH1) mutation, 1p/19q-deficiency, and O-6-methylguanine-DNA methyltransferase methylation." (PMID 36159801, 2022).